FCGR2A (Fc gamma receptor IIa)
Description:
Binds to the Fc region of immunoglobulins gamma. Low affinity receptor. By binding to IgG it initiates cellular responses against pathogens and soluble antigens. Promotes phagocytosis of opsonized antigens.
Synonyms: Fc-gamma-RIIa; CD32; FCG2; FCGR2A1; IGFR2; CD32A; CDw32; FcgammaRIIa; FCGR2; FcGR
Tractability: Small molecule: a structure with a bound ligand is known. Antibody: UniProt places it where antibodies can reach, with high confidence; its Gene Ontology location is reachable by antibodies, with high confidence; UniProt predicts a signal peptide or a membrane-spanning region; the Human Protein Atlas places it where antibodies can reach. PROTAC: ubiquitination databases record sites on it.
Target class: Membrane receptor
Gene: Protein-coding gene on chromosome 1 (161,505,415 to 161,524,013, forward strand). Ensembl gene ENSG00000143226.
Subcellular location: Cell membrane
Subcellular location (Human Protein Atlas): Plasma membrane; Golgi apparatus
Pathways (Reactome):
Immune System: FCGR activation; Neutrophil degranulation; Regulation of actin dynamics for phagocytic cup formation; Role of phospholipids in phagocytosis
Disease: FCGR3A-mediated IL10 synthesis
Gene Ontology:
Molecular function: protein binding; IgG binding; IgG receptor activity
Biological process: antibody-dependent cellular cytotoxicity; cell surface receptor signaling pathway; positive regulation of phagocytosis; positive regulation of tumor necrosis factor production; Fc-gamma receptor signaling pathway
Cellular component: plasma membrane; external side of plasma membrane; secretory granule membrane
Genetic constraint (gnomAD): Loss-of-function variants: 18 observed, 28.94 expected, observed/expected ratio (o/e) 0.62, 90% interval 0.43 to 0.92. The upper end of that interval is the gene's LOEUF score, 0.92, which puts it in group 3 of 6, group 1 being the genes least tolerant of losing a copy. Missense variants: 287 observed, 395.49 expected, observed/expected ratio (o/e) 0.73, 90% interval 0.66 to 0.8. Synonymous variants: 126 observed, 140.06 expected, observed/expected ratio (o/e) 0.9, 90% interval 0.78 to 1.04.
Homologues: Orthologues: macaque FCGR2A (88% identical), chimpanzee FCGR2A (80% identical), guinea pig Fcgr2b (47% identical), dog FCGR2B (45% identical), mouse Fcgr2b (42% identical), rat Fcgr2b (39% identical), mouse Fcgr3 (38% identical), rat Fcgr2a (37% identical), rat Fcgr2al1 (36% identical), rat Fcgr2a (35% identical). Paralogues in human: FCGR2C (85% identical), FCGR2B (67% identical), FCGR3A (34% identical), FCGR3B (33% identical), FCGR1A (29% identical), FCRL5 (26% identical), FCER1A (25% identical), FCRLB (22% identical), FCRL3 (22% identical), FCRL4 (21% identical), FCRLA (18% identical), PECAM1 (17% identical), and 5 more.
Diseases named in the same sentence as FCGR2A in open-access papers:
FCGR2A is named in the same sentence as 168 diseases in open-access papers, as found by Europe PMC text mining. Sharing a sentence is not in itself a finding about the gene and the disease. The quoted sentences say what the papers report.
systemic lupus erythematosus (33 papers, 2008 to 2025). An autoimmune multi-organ disease typically associated with vasculopathy and autoantibody production. "We highlighted an association between the FCGR3B-NA1/NA1 and FCGR3A-158F alleles and systemic lupus erythematosus, in addition to an association between FCGR2A-131R and lupus nephritis." (PMID 40728959, 2025). "All pQTLs were located in non-coding regions of the genome, but one SNP was in complete LD with a missense SNP in FCGR2A (rs1801274, His167Arg) previously associated with systemic lupus erythematosus, ulcerative colitis and Kawasaki disease." (PMID 33104735, 2020). "In another meta-analysis, the His131Arg polymorphism in the FCGR2A gene was found to be associated with susceptibility to systemic lupus erythematosus and lupus nephritis in Asian populations." (PMID 27267995, 2016). "FCGR2A [131R/H] is considered to be a heritable risk factor for a variety of infectious and inflammatory autoimmune diseases, including systemic lupus erythematosus, rheumatoid arthritis, malaria, multiple sclerosis, and anti-neutrophil cytoplasmic auto-antibody positive systemic vasculitis." (PMID 31249568, 2019). "FCGR2A gene polymorphism was reportedly associated with the susceptibility of inflammation-related diseases, such as atherosclerosis, Takayasu arteritis, systemic lupus erythematosus (SLE), and ulcerative colitis." (PMID 34285919, 2021). "FCGR2A/FCGR3A has been reported to be a susceptibility gene for other autoimmune diseases, such as systemic lupus erythematosus, rheumatoid arthritis, multiple sclerosis, type 1 diabetes and ulcerative colitis." (PMID 27769046, 2017). "We compared the frequencies of the functional SNPs of FCGR2A (FcγRIIa-H131R, rs1801274), FCGR2B (FcγRIIb-I232T, rs1050501), FCGR3A (FcγRIIIa-V158F, rs396991) and FCGR3B variants (FcγRIIIb NA1 and NA2) between lupus and healthy controls in an indigenous African Caribbean population." (PMID 40728959, 2025). "Recent genome-wide association studies in lupus patients have identified single nucleotide polymorphisms in or near ITGAM and FCGR2A (the genes for CR3 and Fcγ receptor II, respectively), supporting a potential role for variants of these genes in lupus susceptibility." (PMID 18811944, 2008). "The available data suggest that the FCGR2A plays a pivotal role in the interferon response in systemic lupus erythematosus (SLE), functioning by internalizing immune complexes (ICs) composed of DNA–IgG." (PMID 39857814, 2025). "This signal was shared with ulcerative colitis (UC, PP > 95.3%), systemic lupus erythematosus (SLE, PP > 82.6%) and various cell surface markers of different immune cell populations, including FCGR2A (CD32)." (PMID 34819519, 2021). "The rs4657041 was the lead intronic cis-pQTL for FCGR2A and FCGR2B, which was shared with UC, systemic lupus erythematosus and various cell surface markers of different immune cell populations." (PMID 39512756, 2024). "FCGR3B, FCGR2A and ITGAM are immune-related genes, all of which are known as biomarkers for systemic lupus erythematosus." (PMID 33602227, 2021). "In contrast, the unique genes of the lupus group are more involved in pathogen recognition and degradation, such as TLR7, and FCGR2A." (PMID 33324666, 2020). "In particular, single nucleotide polymorphisms (SNPs) in FCGR2A (R131H), FCGR2B (I232T) FCGR3A (V158F) and FCGR3B (NA1/NA2), have been reported in association with systemic lupus erythematosus (SLE), rheumatoid arthritis (RA) and/or idiopathic thrombocytopenia purpura (ITP)." (PMID 20957197, 2010). "By KEGG pathway analysis, six genes, i.e., C4A, C4B, FCGR2A, HLA-DMA, HLA-DRA, and HLA-DRB1, were enriched as the top 2 significant results in the pathways of Staphylococcus aureus infection (KEGG term hsa05322, FDR = 1.42E−05) and systemic lupus erythematosus (KEGG term hsa05150, FDR = 2.00E−04)." (PMID 34804021, 2021).
autoimmune disease (26 papers, 2011 to 2025). A disorder resulting from loss of function or tissue destruction of an organ or multiple organs, arising from humoral or cellular immune responses of the individual to their own tissue constituents. "A meta-analysis systematically evaluated FCGR2A/3A gene variants in autoimmune diseases (ADs) using four genetic models: dominant, recessive, overdominant, and allelic contrast." (PMID 41000382, 2025). "By aggregating data from multiple studies, the meta-analysis provides a more robust estimate of the genetic effect of FCGR2A rs1801274 on autoimmune disease susceptibility." (PMID 41000382, 2025). "A meta-analysis study has revealed a significant association between an FCGR2A variant and autoimmune diseases, including T1D." (PMID 39371824, 2024). "FCGR2A gene, associated with risks of various autoimmune diseases, has a protective effect against UC and CD through its functional variant FCGR2A*519G." (PMID 39144148, 2024). "The FCGR2A polymorphism has also been implicated in autoimmune diseases: lupus erythematosus, Kawasaki disease, rheumatoid arthritis or ulcerative colitis." (PMID 37892617, 2023). "Considering other autoimmune diseases, associations with Kawasaki disease and ulcerative colitis have also been demonstrated for FCGR2A rs1801274." (PMID 35629038, 2022). "As mice do not express FcγRIIA homologs, transgenic mice expressing the Fcgr2a human gene encoding the R131 variant develop spontaneously autoimmune diseases such as pneumonitis, glomerulonephritis and RA." (PMID 31057544, 2019). "Because of the linkage disequilibrium and given these functional data, it is more likely that 2B.4 variant or FCGR2C-ORF confer the increased risk for autoimmune disease than FCGR2A-p.62Trp." (PMID 31632391, 2019). "A total of 43 relevant studies with the FCGR2A rs1801274 polymorphism and autoimmune diseases were identified through PubMed and Web of Science search, and 17 articles included KD, UC, CD, ATD, RA, T1D and SLE met the inclusion criteria for analysis." (PMID 27270653, 2016). "The aim of this meta-analysis was to estimate the association between the FCGR2A rs1801274 polymorphism and the susceptibility to autoimmune diseases more precisely." (PMID 27270653, 2016). "In summary, the meta-analysis demonstrated that the FCGR2A rs1801274 polymorphism was associated with the susceptibility to multiple autoimmune diseases including KD and UC." (PMID 27270653, 2016). "The FCGR2A rs1801274 polymorphism in multiple autoimmune diseases provides further evidence supporting the concept of common gene underlying multiple autoimmune diseases." (PMID 27270653, 2016). "There have also been two intergenic SNPs identified (rs2099684 and rs10919543) between FCGR2A and FCGR3A that have been associated with the autoimmune disease Takayasu arteritis in Turkish, North American and Chinese Han populations." (PMID 39345014, 2024). "The aim of this systematic review with meta-analysis was to examine the association between the polymorphisms rs1801274 (FCGR2A H131R) and rs396991 (FCGR3A F158V) and susceptibility to autoimmune diseases (ADs), with a focus on the progress and novelty of studies published over the last two decades." (PMID 41000382, 2025). "Although a functional SNP (rs1801274) and methylation sites of FCGR2A has been previously reported to be associated with KD and other autoimmune diseases, these studies did not consider gender differences and their role in KD." (PMID 28886140, 2017). "Additionally, the results suggest that both the FCGR2A (rs1801274) and FCGR3A (rs396991) polymorphisms may be associated with susceptibility to various autoimmune diseases in both European and East Asian populations." (PMID 41000382, 2025). "Thus, our results indicate that FCGR2A/FCGR3A might be a susceptibility gene for TA in patients from the Chinese Han population, suggesting that TA might share associated genetic loci with other autoimmune diseases." (PMID 27769046, 2017).
autoimmune disease (continued). "In the studies of genetic predisposition to develop autoimmune disorders, CNV was proven only for FCGR2C, FCGR3A and FCGR3B, but not for FCGR2A and FCGR2B genes." (PMID 28472129, 2017).
rheumatoid arthritis (24 papers, 2005 to 2025). A chronic, systemic autoimmune disorder characterized by inflammation in the synovial membranes and articular surfaces. "We identified rs7515174 (G-allele, allele frequency = 11.2%) as an intronic cis-pQTL unique to FCGR2A measured by Olink (beta = −1.25, p value < 7.5 × 10−41) and a shared signal with rheumatoid arthritis (RA) in Europeans31 (beta = −0.11, PP > 84.9%)." (PMID 34819519, 2021). "Conversely, a protective association was found between FCGR2A R131 and rheumatoid arthritis." (PMID 41000382, 2025). "For autoimmune rheumatic diseases, the data are mainly related to rheumatoid arthritis, and two meta-analyses have been performed showing the impact of FCGR2A rs1801274." (PMID 35629038, 2022). "FCGR2A A>G (rs1801274) was analyzed because the association between this gene polymorphism and therapeutic response to IFX was reported in patients with rheumatoid arthritis." (PMID 30286108, 2018). "Conversely, the overall analysis identified a negative association between the FCGR2A H131R polymorphism and rheumatoid arthritis in two genetic models (dominant: OR 0.83, 95% CI 0.69-1.00, for HR + RR vs. HH; allelic comparison: OR 0.86, 95% CI 0.76-0.97, for R vs. H)." (PMID 41000382, 2025). "For instance, Caucasian rheumatoid arthritis (RA) patients with the AA genotype in FCGR2A rs1801274 exhibited a higher remission rate 6 months after RTX treatment." (PMID 38739094, 2024).
Kawasaki disease (17 papers, 2012 to 2025). A rare inflammatory disease characterized by an acute febrile, systemic, self-limiting, medium-vessel vasculitis primarily affecting children. "MPO showed association with the products of three Kawasaki disease genes (FCGR2A, CASP3, and LTA) and one related to MIS-C (CYBB)." (PMID 36510129, 2022). "GWAS studies identified the FCGR2A-131H allelic variant with lower affinity for CRP as a susceptibility marker for Kawasaki disease in male patients, a pediatric vasculitis associated with coronary artery aneurysms." (PMID 35203703, 2022). "It is also interesting to note that other polymorphisms in FCGR2A have been associated with Kawasaki disease." (PMID 33981715, 2021). "In summary, our study indicated a significant association between the promoter methylation of FCGR2A, susceptibility of Kawasaki disease, and therapeutic outcomes of IVIG treatment." (PMID 26089602, 2015). "Recent genome-wide association study found rs1801274, a functional single nucleotide polymorphism (SNP) in IgG receptor gene FCGR2A, was associated with increased risk of Kawasaki disease (KD)." (PMID 25093412, 2014). "Another secondary phenotype may be gender, as research suggests a link to male-specific association of polymorphisms in FCGR2A gene with Kawasaki disease." (PMID 33692975, 2021). "Previous studies have also demonstrated that FCGR2A is the susceptibility gene for Kawasaki disease (KD), while levels in methylation of its CpG site promoter could act as a crucial biomarker for optimizing intravenous immunoglobulin (IVIG) therapy." (PMID 34421979, 2021). "Furthermore, a genome-wide association study (GWAS) has revealed FCGR2A-p.166His to be strongly associated with susceptibility to Kawasaki disease, a pediatric vasculitis affecting the coronary vasculature in particular." (PMID 31632391, 2019). "On the other end, a relatively more active immune response, conferred by FCGR2A-p.166His, is associated with the development of ITP, Kawasaki disease and inflammatory bowel disease, emphasizing the intricate role of FCGR2A at the interface of multiple pathways leading to autoimmunity." (PMID 31632391, 2019). "DNA methylation is one of the epigenetic mechanisms that control gene expression; thus, we hypothesized that methylation status of CpG islands in FCGR2A promoter associates with the susceptibility and therapeutic outcomes of Kawasaki disease." (PMID 26089602, 2015). "FCGR2A rs1801274 allele A and the risk of Kawasaki disease in meta-analysis." (PMID 25093412, 2014). "In this study, we designed experiments to investigate the association between methylation status of CpG islands on FCGR2A promoter and the clinical outcomes of IVIG therapy in Kawasaki disease." (PMID 26089602, 2015). "Additionally, we investigated genes linked to Kawasaki disease (CD40 rs4813003, FCGR2A rs1801274, CASP3 rs113420705) that play roles in immunogenesis." (PMID 40066463, 2025). "In brief, notwithstanding a direct link between FCGR2A and COVID-19 has not been identified yes, it appears quite intriguing that this gene has previously been associated to Kawasaki disease, which in turn has been associated to COVID-19." (PMID 33981715, 2021). "Additionally, by examining genes associated with Kawasaki disease (CD40, FCGR2A, CASP3), our study highlights potential common pathways in hyperinflammatory responses, suggesting that insights gained from COVID-19 could be applicable to other pediatric inflammatory conditions." (PMID 40066463, 2025).
malaria (17 papers, 2008 to 2025). Malaria is a serious and sometimes fatal disease caused by a parasite that commonly infects a certain type of mosquito which feeds on humans. "The rs1801274 coding mutation in the FCGR2A gene, which encodes the FcγRIIA/CD32a for the Fc fragment of IgG, has been implicated in various diseases, including malaria." (PMID 37958695, 2023). "Another example is the IgG receptor FcγRIIa, encoded by FCGR2A, such that H131 homozygotes displayed higher IgG2 levels and were protective against high parasitemia and onset of malaria symptoms as shown in a causal diagram." (PMID 25887595, 2015). "Although IgG2 generally binds Fc receptors with low affinity, IgG2 levels were associated with a protective effect against malaria among individuals homozygous for the FCGR2A H131 variant, which influences binding of IgG2 on neutrophils." (PMID 25887595, 2015). "Variations in several host genes (HBB, IL4, IL12, TNF, LTA, NCR3 and FCGR2A) have been reported to be associated with malaria outcome." (PMID 24066864, 2013). "It should be stressed that a limited number of genes have been associated with mild or severe malaria in several independent studies; these include FCGR2A that encodes the human IgG receptor FcγRIIa." (PMID 22947458, 2012). "This study was planned to make a further contribution to solving the problem of the real role of the most common polymorphisms of TLR4, TLR9, TIRAP and FCGR2A in modulating the risk of malaria and disease severity." (PMID 22691414, 2012). "These include HBB, IL4, TNF, and FCGR2A, which have also been associated with both malaria resistance and IgG levels." (PMID 22947458, 2012). "In the present study, we successfully elucidated associations between FCGR3B and FCGR2A polymorphisms and clinical malaria using data from a well characterised longitudinal cohort study." (PMID 23049979, 2012). "Furthermore, HBB, IL4, TNF, and FCGR2A have been associated with both malaria resistance and IgG levels." (PMID 22947458, 2012). "HBB, IL4, IL12, TNF, LTA, NCR3 and FCGR2A polymorphisms have been associated with malaria resistance in humans, whereas cytophilic immunoglobulin G (IgG) antibodies are thought to play a critical role in immune protection against asexual blood stages of the parasite." (PMID 22947458, 2012). "This study was planned to make a further contribution to solving the problem of the real role of the most common polymorphisms of TLR4, TLR9, TIRAP and FCGR2A genes in modulating the risk of malaria and disease severity in children from Burundi, Central Africa." (PMID 22691414, 2012). "The association of GLURP R2 IgG2 titres with reduced risk of malaria in the Burkinabe cohort may be due to the observation that IgG2 binds with high affinity to Fc gamma receptor IIA-131H (FcγRIIA-131H) allele on immune cells of individuals expressing this variant." (PMID 26921176, 2016). "For example, FCGR2A-131H and FCGR2B-232T alleles are associated with a protective effect against malaria and against its most deadly forms." (PMID 40728959, 2025). "In this study, we explored the influence of Single Nucleotide Polymorphisms (SNP) in exon 4 of FCGR2A and in exon 3 of FCGR3B in a cohort of Beninese infants followed-up for malaria from birth to 24 months of age." (PMID 36499205, 2022). "Using PCR-ASRED and exon 3 nucleotide sequencing data for FCGR2A and FCGR3B respectively, the association between SNPs which alter the affinity of these receptors for IgG subclasses and clinical malaria were studied in a cohort of Ghanaian children." (PMID 23049979, 2012). "Finally, genetic variants of FCGR2A, an immunoglobulin G receptor, could be associated with an increased risk of malaria because of a significant reduction in its binding capacity for IgG and C reactive protein (CRP) and the consequent reduced phagocytosis of IgG and CRP opsonized structures." (PMID 22691414, 2012).